MIR5579 (microRNA 5579)
Synonyms: hsa-mir-5579
Gene: MicroRNA gene on chromosome 11 (79,422,169 to 79,422,226, reverse strand). Ensembl gene ENSG00000266570.
Homologues: Orthologues: chimpanzee MIR5579 (100% identical).